CFTR (CF transmembrane conductance regulator)
Diseases named in the same sentence as CFTR in open-access papers (continued):
Sharing a sentence is not in itself a finding about the gene and the disease.
cystic fibrosis (continued). "It is characterized by mutations in the Cystic Fibrosis Transmembrane Conductance Regulator (CFTR) gene, which cause multifunctional defects that lead to recurrent infections with consequent lung hyperinflammation and lung tissue damage in CF patients." (PMID 36009490, 2022). "Besides the benefits already brought to cystic fibrosis patients by CFTR modulators approved so far, novel drugs are eagerly awaited to design novel combinations that could further increase the efficacy of cystic fibrosis treatment." (PMID 36293130, 2022). "The vast majority of people with cystic fibrosis are now eligible for CF transmembrane regulator (CFTR) modulator therapy." (PMID 35900863, 2022). "Next, recombinant adenovirus (Ad/CFTR) wasemployed for gene therapy for cystic fibrosis through the delivery of thecystic fibrosis transmembrane conductance regulator (CFTR)cDNA." (PMID 36206378, 2022). "However, the CFTR gene also affects the salivary glands of patients with Cystic Fibrosis." (PMID 35627903, 2022). "Cystic fibrosis is a genetic disease resulting in dysfunction of CFtransmembrane conductance regulator (CFTR) protein." (PMID 36380568, 2022). "In cystic fibrosis therapy, the recent approval of CF-transmembrane conductance regulator (CFTR) channel modulators is considered to be the major breakthrough." (PMID 34025651, 2021). "Patients with cystic fibrosis harboring the P67L variant in the cystic fibrosis transmembrane conductance regulator (CFTR) often exhibit a typical CF phenotype, including severe respiratory compromise." (PMID 33781744, 2021). "The loss of function of cystic fibrosis transmembrane conductance regulator (CFTR), in people with cystic fibrosis, causes airway surface dehydration, mucus build‐up, inflammation, and bacterial infections that lead to lung failure." (PMID 34382377, 2021). "Therefore, it becomes crucial to understand the effects of such modulation of CFTR function on the airway physiology, especially on airway infections and inflammation that are currently the major life-limiting factors in people with cystic fibrosis." (PMID 33816324, 2021). "Cystic fibrosis (CF; OMIM 219700) is a common monogenic disease caused by a mutation of the CFTR gene (CFTR, OMIM 602421; reference sequence accession number NM_000492.3)." (PMID 34220950, 2021). "Prognosis of patients with cystic fibrosis varies extensively despite recent advances in targeted therapies that improve CF transmembrane conductance regulator (CFTR) function." (PMID 33796025, 2021). "The landscape of clinical care and treatment for individualswith cystic fibrosis is poised for remarkable change after the discovery of a noveldisease-modifying therapy that restores protein function to the CFTR (CF transmembraneregulator)." (PMID 33465316, 2021). "We previously reported that expression of a miR-138 mimic or knockdown of SIN3A in primary cultures of cystic fibrosis airway epithelia increased ΔF508-CFTR mRNA and protein levels, and partially restored CFTR-dependent chloride transport." (PMID 34717611, 2021). "It is well known that CFTR has been widely studied in cystic fibrosis, and recently, it has grown interest to study its role in other diseases or inflammatory conditions such as in the biliary epithelium and intestine." (PMID 34512749, 2021). "Mutations of the gene encoding cystic fibrosis transmembrane conductance regulator (CFTR) lead to CF." (PMID 33584832, 2021). "A deficiency in cystic fibrosis transmembrane conductance regulator (CFTR) function in CF leads to chronic lung disease." (PMID 33613309, 2021). "A well-documented case is the autosomal recessive disorder cystic fibrosis, which is caused by LOF mutations of a chloride ion channel, cystic fibrosis transmembrane conductance regulator (CFTR)." (PMID 33837739, 2021).
cystic fibrosis (continued). "Cystic fibrosis (CF, MIM: 219700) is an autosomal recessive genetic disease characterized by mutations in the cystic fibrosis transmembrane conductance regulator (CFTR, MIM: 602421) gene." (PMID 33713579, 2021). "Enhanced F508del rescue by CFTR modulators is achieved by exposing F508del/F508del primary cultures of human bronchial epithelia to relevant inflammatory stimuli, i.e., supernatant from mucopurulent material or bronchoalveolar lavage fluid from human cystic fibrosis airways." (PMID 34831482, 2021). "In CF, transepithelial Cl− and HCO3− transport is impaired due to mutations in the gene encoding the cystic fibrosis transmembrane conductance regulator (CFTR) protein, which functions as a cAMP/PKA-regulated epithelial anion channel." (PMID 34253193, 2021). "Cystic fibrosis is a heritable, multiorgan disease that impacts all tissues that normally express cystic fibrosis transmembrane conductance regulator (CFTR) protein." (PMID 34339302, 2021). "Cystic fibrosis (CF, OMIM 219700) is a life-threatening monogenic recessive disorder due to mutations in the cystic fibrosis transmembrane conductance regulator (CFTR) gene (OMIM*602421)." (PMID 33946859, 2021). "Cystic fibrosis is a genetic disease involving compromised function of cystic fibrosis transmembrane conductance regulator (CFTR) that leads to impaired airway host defense and therefore causes lung inflammation and bacterial infections." (PMID 34867864, 2021). "There is a variety of ion channels, including the cystic fibrosis transmembrane conductance regulator (CFTR), that allow AECs to control the trans-epithelial water flow and as such, controls the viscosity of the mucus and efficacy of the MCC." (PMID 34122136, 2021). "The SNV rs148505224 associated with low GRS T1D maps to the CF transmembrane conductance regulator (CFTR) gene, i.e., the gene mutated in cystic fibrosis and a cause of pancreatitis." (PMID 34302048, 2021). "Mutations in the Cystic Fibrosis Transmembrane Conductance Regulator (CFTR) gene lead to impaired chloride secretion and poor mucociliary clearance, making CF patients prone to lung infections." (PMID 33690714, 2021). "The emergence of highly effective CFTR modulator therapy has led to significant improvements in health care for most patients with cystic fibrosis." (PMID 33923202, 2021). "The role of S1P in Cystic Fibrosis has been investigated since 2001, when it was first described that the CFTR channel regulates the inward transport of S1P." (PMID 34572307, 2021). "Therefore, if on the one hand, the use of ex vivo models allow evaluating the drug responsiveness regardless of the patient’s genotype, on the other hand, the study of the CFTR interactome is of fundamental importance for the search for new therapeutic targets for cystic fibrosis." (PMID 34356748, 2021). "There is a considerable variation in the phenotype and course of the disease in CF even in patients with the same cystic fibrosis transmembrane conductance regulator (CFTR) genotype, suggesting that other factors are important for their prognosis." (PMID 33679736, 2021). "A contribution of the cystic fibrosis transmembrane conductance regulator (CFTR) to this process has been suggested." (PMID 34354180, 2021). "Moreover,we developed and verified a new methodology using the red/green fluorescenceratio and one- or two-photon excitation to monitor the flow of chloridein cells, and using a specific CFTR inhibitor, cystic fibrosis conditionswere simulated in the cell model." (PMID 34148347, 2021). "CF is inherited in an autosomal recessive manner and it is a typical monogenic disease, yet it may be caused by over 2100 kinds of mutations located in the gene encoding the cystic fibrosis transmembrane conductance regulator (CFTR) protein, with more still being discovered." (PMID 33919435, 2021).
cystic fibrosis (continued). "Decreased human epididymis protein 4 (HE4) plasma levels were reported in cystic fibrosis patients under CFTR potentiator ivacaftor therapy, which inversely correlated with lung function improvement." (PMID 34054511, 2021). "While approximately 2000 mutations have been discovered in the gene coding for the cystic fibrosis transmembrane conductance regulator (CFTR), only a small amount (about 10%) is associated with clinical cystic fibrosis disease." (PMID 33800499, 2021). "The availability of a simple, robust and non-invasive in vitro airway model would be useful to study the functionality of the cystic fibrosis transmembrane regulator (CFTR) protein and to personalize modulator therapy for cystic fibrosis patients." (PMID 34330959, 2021). "Cystic fibrosis is an inherited genetic disease leading to cystic fibrosis transmembrane conductance regulator (CFTR) dysfunction." (PMID 34869102, 2021). "Analysis of sweat chloride levels in cystic fibrosis patients is essential not only for diagnosis but also for the monitoring of therapeutic responses to new drugs, such as cystic fibrosis transmembrane conductance regulator (CFTR) modulators and potentiators." (PMID 32933070, 2020). "Similarly to cystic fibrosis, CBAVD is caused by mutations in the CFTR gene." (PMID 32722328, 2020). "Cystic fibrosis transmembrane conductance regulator (CFTR)-rescuing drugs have already transformed cystic fibrosis from a fatal disease to a treatable chronic condition." (PMID 32244346, 2020). "CFTR dysfunction results in a severe disease known as cystic fibrosis, characterized by impaired epithelial transport in the respiratory system, liver, and pancreas." (PMID 32308537, 2020). "The gene responsible for CF is named the cystic fibrosis transmembrane conductance regulator (CFTR) and was sequenced in 1989." (PMID 31828483, 2020). "Therefore, USP10 expression may be advantageous in cystic fibrosis patients to promote CFTR recycling to the epithelial surface." (PMID 33277473, 2020). "Indeed, specific autophagy and ESCRT components participate in cystic fibrosis transmembrane conductance regulator (CFTR) unconventional secretion, thus suggesting that the autophagic machinery may play a specific role in cystic fibrosis pathogenesis." (PMID 32276321, 2020). "The treatment of cystic fibrosis has been transformed by orally-bioavailable small molecule modulators of the cystic fibrosis transmembrane conductance regulator (CFTR), which restore function to CF mutants." (PMID 31902693, 2020). "Cystic fibrosis is an autosomal recessive disorder leading to a dysfunctional cystic fibrosis transmembrane regulator (CFTR) affecting various organs." (PMID 33348735, 2020). "Cystic fibrosis (CF; OMIM #219700, ORPHA:586) is an autosomal recessive genetic disease, caused by loss-of-function mutations in the CF transmembrane conductance gene (CFTR; OMIM *602421)." (PMID 31900120, 2020). "The most common disease-causing mutation in the Cystic Fibrosis Transmembrane Conductance Regulator (CFTR) gene, F508del, leads to cystic fibrosis, by arresting CFTR processing and trafficking to the plasma membrane." (PMID 32117984, 2020). "Although heterozygous carriers of pathogenic CFTR variants do not develop cystic fibrosis, they may have an approximately 4–10-fold increased risk for pancreatitis and associated pancreatic injury due to elevated mucus levels, fibrosis, and cyst formation." (PMID 32425982, 2020). "Cystic fibrosis is a multisystemic autosomal recessive disorder related to alteration of the structure of the CF transmembrane conductance regulator (CFTR)." (PMID 32471113, 2020). "This phenomenon is particularly well illustrated by some mutations in the Cystic Fibrosis Transmembrane conductance Regulator (CFTR) protein, responsible for Cystic Fibrosis." (PMID 32650630, 2020). "Anionophores replacing the defective CFTR activity in cystic fibrosis patients represent promising drug candidates for CF therapy." (PMID 32168979, 2020).
cystic fibrosis (continued). "Similarly to cystic fibrosis, congenital bilateral absence of the vas deferens is caused by mutations in the CFTR gene." (PMID 32722328, 2020). "Finally, no patients in this study were diagnosed with cystic fibrosis, although examinations to definitely exclude this disease, such as CFTR polymorphisms, deltaF508 heterozygosity, and sweat chloride tests, were not performed." (PMID 32370226, 2020). "The clinical manifestation of cystic fibrosis is heterogeneous also in patients with the same cystic fibrosis transmembrane regulator (CFTR) genotype and in affected sibling pairs." (PMID 32242045, 2020). "Treatment of cystic fibrosis is an exemplar of this paradigm as the development of CFTR modulator therapies has allowed for targeted and effective treatment of individuals harboring specific genetic variants." (PMID 33085659, 2020). "Cystic fibrosis is due to mutations in the CF-transmembrane conductance regulator (CFTR) and CF-related diabetes (CFRD) is its most common co-morbidity, affecting ~50% of all CF patients, significantly influencing pulmonary function and longevity." (PMID 33264332, 2020). "In cystic fibrosis, cystic fibrosis transmembrane regulator (CFTR) dysfunction leads to digestive disorders that promote intestinal inflammation and dysbiosis enhancing gastrointestinal symptoms." (PMID 33348735, 2020). "In the last 5 years, several studies have investigated the role of lipid composition and dynamics of the plasma membrane in the trafficking of cystic fibrosis transmembrane conductance regulator (CFTR), the anion transporter defective in CF." (PMID 32673287, 2020). "Cystic fibrosis is an autosomal recessive disorder characterized by the abnormal functioning of the CF transmembrane conductance regulator (CFTR) protein that is essential for the regulation of transmembrane chloride reabsorption." (PMID 33213453, 2020). "Identification of the cystic fibrosis transmembrane conductance regulator (CFTR) gene and its numerous variants opened the way to fantastic breakthroughs in diagnosis, research and treatment of cystic fibrosis." (PMID 32512765, 2020). "All of these manifestations are hallmarks of cystic fibrosis and could arise from or be aggravated by deficient CFTR activity: in this context, it is intriguing to hypothesize that a substantial subset of COVD-19 cases would benefit from the use of cystic fibrosis medications." (PMID 33250777, 2020). "Discovery of the cystic fibrosis transmembrane conductance regulator (CFTR) gene was the long-awaited scientific advance that dramatically improved the diagnosis and treatment of cystic fibrosis." (PMID 32276344, 2020). "This review focuses on the ubiquitylation mechanism that contributes to the stability of mutant CFTR at the endoplasmic reticulum (ER) and post-ER compartments and discusses the possibility as a pharmacological target for cystic fibrosis." (PMID 32331485, 2020). "Functional profiling of CFTR-directed therapeutics offers the potential to provide significant benefits to young people with cystic fibrosis." (PMID 33014932, 2020). "In contrast to mouse CFTR-knockout models for cystic fibrosis, the CF pig model accurately reproduces human CF lung pathology." (PMID 32712714, 2020). "Finally, we selected to study cystic fibrosis in our HIO model based on the suitability of these organoids to study the epithelial expression of CFTR in the intestine, in addition to the established assays to measure CFTR function using primary rectal organoids." (PMID 31924806, 2020). "In 1989 Choi, Collins, and colleagues used linkage-based techniques to identify the gene responsible for CF, which they named the Cystic Fibrosis Transmembrane conductance Regulator (CFTR)." (PMID 32414011, 2020).
cystic fibrosis (continued). "The deletion of phenylalanine at position 508 (F508del) in cystic fibrosis transmembrane conductance regulator (CFTR) causes a severe defect in folding and trafficking of the chloride channel resulting in its absence at the plasma membrane of epithelial cells leading to cystic fibrosis." (PMID 31143125, 2019). "Cystic fibrosis is a genetic disorder of the epithelial CFTR apical chloride channel resulting in multi-organ manifestations, including pancreatic exocrine secretion." (PMID 31296159, 2019). "Cystic fibrosis, the most common inherited disease in Caucasian populations is due to alteration of the CFTR gene." (PMID 30620748, 2019). "CF is caused by a mutation in the cystic fibrosis transmembrane conductance regulator (CFTR) gene resulting in an increased mucous viscosity in CF lungs." (PMID 30974814, 2019). "F508del‐cystic fibrosis transmembrane conductance regulator (CFTR) is the major mutant responsible for cystic fibrosis." (PMID 32123813, 2019). "Recently, iPSCs from cystic fibrosis patients were used to characterize the impact of cystic fibrosis transmembrane conductance regulator (CFTR) on pancreatic commitment and to model pancreatic aspects of the disease." (PMID 30930950, 2019). "Potentiator/co-potentiator combination therapy may be effective in a subset of minimal function missense, nonsense and deletion mutations in CFTR that cause cystic fibrosis and are not responsive to current CFTR modulator combinations." (PMID 31776420, 2019). "Mutations in the Cystic Fibrosis Transmembrane Conductance Regulator (CFTR) gene lead to cystic fibrosis." (PMID 31590401, 2019). "In addition, the lack of symptoms of cystic fibrosis in the intestines of some CFTR-deficient mice also suggests the presence of an alternative secretion pathway." (PMID 31383845, 2019). "The cystic fibrosis transmembrane conductance regulator (CFTR) chloride channel is dysfunctional in CF, leading to defects in epithelial transport." (PMID 30761000, 2019). "Using a M. abscessus infected CF zebrafish model, it was demonstrated that CFTR (cystic fibrosis transmembrane conductance regulator) dysfunction seems to have a specific role in the immune control of M. abscessus infections only." (PMID 31766758, 2019). "Given that Cftr−/− mice do not develop the airway pathology observed in patients with cystic fibrosis, the effects of CFTR deficiency on B cell function and activation observed in murine analyses may be more pronounced or altered in human disease." (PMID 31262295, 2019). "Moderate gene transfer efficiency was observed for cationic liposome-mediated delivery of the cystic fibrosis transmembrane conductance regulator (CFTR) gene." (PMID 31546908, 2019). "CF is the most common inherited disease among Caucasians and results from one of many types of defects of the cystic fibrosis transmembrane conductance regulator (CFTR) ion channel." (PMID 30910901, 2019). "IEC monolayers derived from the Cystic Fibrosis mouse model CFTR ∆F508 fail to respond to CFTR activator forskolin in 3D matrigel culture as measured by spheroid swelling and transwell monolayer culture via Ussing chamber electrophysiology." (PMID 30111276, 2018). "Cystic fibrosis is a genetic lethal disease, originated from the defective function of the CFTR protein, a chloride and bicarbonate permeable transmembrane channel." (PMID 30131695, 2018). "The emerging use of cystic fibrosis transmembrane conductance regulator (CFTR) modulators has provided CF patients with unprecedented access to potentially life-extending therapies." (PMID 30459435, 2018). "These experiments demonstrate that these anionophores have a limited toxicity, and could be used to promote anion transport in cells, i.e., are good candidates to replace the defective or missing CFTR in an attempt to design a new, mutant independent cystic fibrosis therapeutic approach." (PMID 29422673, 2018).